TRAF6 (TNF receptor associated factor 6)
Diseases named in the same sentence as TRAF6 in open-access papers (continued):
Sharing a sentence is not in itself a finding about the gene and the disease.
osteoporosis (24 papers, 2015 to 2026). A condition of reduced bone mass, with decreased cortical thickness and a decrease in the number and size of the trabeculae of cancellous bone (but normal chemical composition), resulting in increased fracture incidence. "At the same time, it can also mediate PI3K/AKT and Nuclear Factor-κB (NF-κB) through RANKL/RANK/ TNF receptor-associated factor 6 (TRAF6) pathway to play an anti-osteoporosis role." (PMID 38474452, 2024). "Altogether, Gds could improve osteoporosis by suppressing high bone turnover via controlling OPG/RANKL/TRAF6 pathway, which is implicated with ovarian steroidogenesis pathway and arachidonic acid metabolism pathway." (PMID 35495954, 2022). "Analysis of protein synthesis using the Western blot technique revealed comparable synthesis levels of fos-related antigen 1 (Fra1), suppressor of cytokine signaling 1 (SOCS1), and the TNF receptor-associated factor 6 (TRAF6) in the non-osteoporosis and osteoporosis groups for both cell types." (PMID 25563300, 2015). "Interestingly, we found that the plasma concentration of TRAF6 was dramatically upregulated in OP patients compared with that in control patients, indicating that the upregulation of TRAF6 could cause osteoporosis." (PMID 39536082, 2024). "The role of the TRAF6/PI3K/AKT cascade in ROS-related osteoporosis was more pronounced when a recent study validated the impact of this cascade on the transcription of malondialdehyde (MDA), superoxide dismutase (SOD), and glutathione (GSH)." (PMID 40496246, 2025). "Elevated RANKL levels, as observed in osteoporosis, lead to enhanced TRAF6-mediated signaling, promoting osteoclastogenesis and bone resorption." (PMID 40496246, 2025). "For example, elevated levels of pro-inflammatory cytokines like TNF-α in osteoporosis can enhance TRAF6 signaling, triggering the increased activity of NF-κB and PI3K/AKT pathways in osteoclasts, thereby promoting osteoclastogenesis and bone resorption." (PMID 40496246, 2025). "Studies indicate that IONPs, specifically ferumoxytol and ferucarbotran, can significantly attenuate osteoclastogenesis in osteoporosis by modulating the TRAF6 signaling pathway." (PMID 40496246, 2025). "For instance, augmented levels of pro-inflammatory cytokines like TNF-α and RANKL in osteoporosis patients enhance TRAF6 and MAPK activation, promoting osteoclast activity and leading to bone loss." (PMID 40496246, 2025). "Based on the pivotal mechanism of the NIP30/REGγ/TRAF6 axis, we determined that TTP22 can alleviate osteoporosis by promoting the ubiquitin-independent proteasomal degradation of TRAF6 and provide a different strategy for the treatment of osteoporosis." (PMID 39536082, 2024). "Collectively, our study reveals that the NIP30/REGγ/TRAF6 axis is critical in osteoporosis and TTP22 is a potential unique drug for osteoporosis treatment." (PMID 39536082, 2024). "In this study, we identified REGγ as a candidate biomarker in osteoporosis and demonstrated that REGγ regulated bone metabolism by degrading TRAF6 in a ubiquitin-independent manner." (PMID 39536082, 2024). "Downregulation of TRAF6 has similarly been shown to curb bone resorption and osteoclast activation in murine osteoporosis models." (PMID 39152382, 2024). "Taken together, these results suggested that NIP30 dephosphorylation inhibits the function of the REGγ-20S proteasome, thereby promoting ubiquitin-independent degradation of TRAF6 to inhibit the development of osteoporosis." (PMID 39536082, 2024). "After the high-dose TMP-Ca chelate treatment, the TRAF6 protein content in the tibia of the retinoic acid-induced osteoporosis rats was significantly reduced to 2.46 ± 0.09 (p < 0.01)." (PMID 39272543, 2024). "Taken together, our data demonstrate that TTP22 can alleviate osteoporosis by inhibiting NIP30/REGγ/TRAF6." (PMID 39536082, 2024).
osteoporosis (continued). "One of the most striking features of the present study is that we identified TRAF6 as a pivotal downstream target of the REGγ-20S proteasome involved in regulating osteoclast activation in the context of osteoporosis." (PMID 39536082, 2024). "In recent years, TRAF6 has been extensively investigated in tumors, immunity, neurodegenerative diseases, ischemic stroke and osteoporosis." (PMID 35668944, 2022). "When compared with SR and puerarin, polyphyllin VII’s antioxidant capability is highly potent, especially in inhibiting the TRAF6-Nox1-mediated ROS pathway, which makes it particularly effective for oxidative stress-induced bone resorption common in osteoporosis." (PMID 40496246, 2025). "Meanwhile, one recent in vivo study has shown that this herb exerted an anti-osteoporosis effect by suppressing the activations of TRAF6 and NFATc1, both of which played imperative roles in osteoclast differentiation during the advancement of periodontal diseases." (PMID 41010928, 2025). "A notable study investigated Epimedium prenylflavonoids (EP), compounds derived from the plant Epimedium, known for their potential in osteoporosis treatment due to their ability to modulate TRAF6—a crucial mediator in osteoclastogenesis and bone resorption pathways." (PMID 40496246, 2025). "Recent studies found that the proteasome system could regulate the function of TRAF6 via degradation, indicating that understanding the regulation of TRAF6 degradation could be a new therapeutic strategy for osteoporosis." (PMID 39536082, 2024). "Considering that the NIP30/REGγ/TRAF6 axis is critical in osteoporosis, we used TTP22 to determine whether it could inhibit the phosphorylation of NIP30 to affect the function of REGγ." (PMID 39536082, 2024). "Importantly, this study revealed that the TMP-Ca chelates regulate the OPG/TRAF6 signaling pathways at a molecular level to adjust bone metabolism providing new perspectives and strategies for treating osteoporosis." (PMID 39272543, 2024). "Similarly, the TRAF6 inhibitor C25-140 exhibits analogous effects, suggesting its potential as a unique therapeutic strategy for treating osteoporosis." (PMID 39536082, 2024). "More importantly, BMM-conditional Traf6 KO with REGγ KO mice could “rescue” the osteoporosis phenotypes." (PMID 39536082, 2024). "Mechanistically, UBA3-induced neddylation is actively involved in activation of the TRAF6-TAK1-NFATc1 signaling pathway-induced RANKL during osteoporosis and osteoclast differentiation, and TRAF6 neddylation at Lys124 is necessary for NF-κB activation induced by IL-17A in CIA." (PMID 38434245, 2023). "At the same time, RANK can bind with several TRAFs to active RANK transmission to the downstream of NF-κB signal pathway, and the binding of RANKL to RANK recruits TRAF6 to stimulate the differentiation of osteoclast, which accelerates bone resorption and leads to osteoporosis." (PMID 35495954, 2022). "In addition, we further confirmed that different doses of the TMP-Ca chelates could effectively regulate the protein expression levels of OPG/TRAF6 in the retinoic acid-induced rat osteoporosis model." (PMID 39272543, 2024). "Furthermore, we found that TTP22 could postpone osteoporosis by regulating theCKII/NIP30/REGγ/TRAF6 axis and could thereby provide a therapeutic approach for osteoporosis treatment." (PMID 39536082, 2024). "We observed a downregulation of TRAF6 expression in Nip304A/4A mice, suggesting that NIP30/REGγ/TRAF6 pathway regulated osteoporosis." (PMID 39536082, 2024). "Ultimately, we determined that AR495 and the fermentation broth group can balance bone metabolism by inhibiting the RANK/RANKL/OPG system, as well as the RANKL/TRAF-6 and TLR4/MYD88 pathways, thereby alleviating osteoporosis." (PMID 39410150, 2024). "Overall, our study reveals a unique function of NIP30/REGγ/TRAF6 axis in osteoporosis and provides a potential therapeutic drug TTP22 for osteoporosis." (PMID 39536082, 2024).
osteoporosis (continued). "RT-qPCR also revealed that the MAPK signaling pathway (p38, TRAF6) and NF-kappa B signaling pathway (c-FLIP, MIP1β) were significantly different between osteoporosis patients and control samples." (PMID 36311708, 2022). "By attenuating TRAF6 signaling and modulating the RANKL pathway, these nanoparticles hold promise in controlling osteoclastogenesis while fostering osteogenesis, marking a significant advancement in osteoporosis therapy." (PMID 40496246, 2025). "Based on NIP30 (a REGγ “inhibitor”) dephosphorylation by CKII inhibition activated the ubiquitin-independent degradation of TRAF6, we selected TTP22, an inhibitor of CKII, and defined that TTP22 could alleviate osteoporosis in vitro and in vivo." (PMID 39536082, 2024). "Moreover, EA inhibited osteoclast differentiation in vitro through the TRAF6-dependent PI3K/Akt and NF-κB signalling pathways and decelerated osteoporosis progression in the OVX rat model." (PMID 39152382, 2024). "In this study, we found that EA inhibited TRAF6, NFATc1, pAKT/AKT and pNF-κB/κB expression downstream of RANK, suppressed osteoclast differentiation, and effectively delayed oxidative stress-induced osteoporosis, consistent with previous studies." (PMID 39152382, 2024). "Furthermore, we analyzed some osteoporosis-related genes, such as ALP, OPG, RUNX2, RANKL and TRAF-6." (PMID 36835176, 2023). "The findings indicated that EA can negatively regulate osteoclastogenesis by inhibiting the TRAF6/PI3K/AKT/NF-κB axis and that ameliorating ovariectomy-induced osteoporosis in rats with EA may be a promising potential therapeutic strategy for the treatment of osteoporosis." (PMID 39152382, 2024). "The relationship between TRAF6, NF-κB, MAPK, and osteoporosis, which are related to pathogenesis, is becoming increasingly evident, further demonstrating the role of inflammation in the induction of osteoporosis and suggesting the possibility of treating osteoporosis through inhibiting inflammation." (PMID 37895909, 2023). "Our results imply that PTE promotes the proliferation and osteogenic differentiation of rBMSCs by upregulating p38 MAPK, STE20, and IGF1R and downregulating TRAF6 expression, which may provide experimental evidence of the potential of PTE in the treatment of osteoporosis." (PMID 30984279, 2019). "Based on the pivotal mechanism of the NIP30/REGγ/TRAF6 axis, we defined that the CKII inhibitor TTP22 could alleviate osteoporosis by promoting the ubiquitin-independent proteasomal degradation of TRAF6 and provided a strategy for the treatment of osteoporosis." (PMID 39536082, 2024). "Additionally, this study indicates that p38 MAPK and its related genes (STE20, IGF1R, and TRAF6) are involved in the mechanism of rBMSCs' osteogenic differentiation, which provides experimental evidence of the potential application of PTE in the treatment of osteoporosis." (PMID 30984279, 2019).
pancreatic cancer (23 papers, 2016 to 2026). "In pancreatic cancer, TNF receptor-associated factor 6 increased the degradation of MST1 via the ubiquitination degradation pathway, overexpressed YAP and regulated tumor cell growth and metastasis." (PMID 38589525, 2024). "For instance, TNF receptor-associated factor 6 (TRAF6) promoted the migration and colony formation of pancreatic cancer cells through the regulation of YAP40." (PMID 33431791, 2021). "The results showed that only TRAF6 was associated with pancreatic cancer prognosis." (PMID 38825674, 2024). "Furthermore, our correlation analysis with clinicopathological features indicates a significant association of TRAF6 expression with the TNM stage of pancreatic cancer." (PMID 38825674, 2024). "NEAT1 competitively binds to miR-146b-5p to attenuate the inhibitory effect of miR-146b-5p on TRAF6, thereby increasing the expression of TRAF6 and promoting the proliferation, migration and invasion of pancreatic cancer cells." (PMID 38970092, 2024). "To further explore the role of TRAF6 in pancreatic cancer, we knocked down TRAF6 in PDAC cells and found that the proliferation, migration, and invasion of PDAC cells were decreased, suggesting that TRAF6 promotes pancreatic cancer progression." (PMID 38825674, 2024). "TRAF6 has been reported to be a significant oncogene in pancreatic cancer, prostate cancer, and nasopharyngeal carcinoma." (PMID 32724313, 2020). "TRAF6 is a significant oncogene in pancreatic cancer, prostate cancer, and nasopharyngeal carcinoma." (PMID 32724313, 2020). "The treatment of pancreatic cancer cells with a combination of PIs and radiation resulted in marked TRAF6 downregulation, enhanced autophagy, and increased cytotoxicity." (PMID 29184971, 2018). "More recently, we also demonstrated that a proteasome inhibitor (MG132) combined with IR enhanced its anti-pancreatic tumor effects through the induction of autophagy and the downregulation of TRAF6." (PMID 29703234, 2018). "The mechanistic role of TRAF6 in PI-induced autophagy in pancreatic cancer cell death was further supported by the fact that autophagy inhibitors significantly reduced the cytotoxicity." (PMID 29184971, 2018). "In pancreatic cancer cells, KRAS mutations induce increased levels of the TNF-receptor family member TRAF6, which has a role in maintaining cell survival." (PMID 29184971, 2018). "Furthermore, CD74 was shown to promote a pro-inflammatory tumor microenvironment in pancreatic cancer by inducing the secretion of S100A8/A9 via activation of TRAF6-NF-κB." (PMID 39425000, 2025). "Bortezomib is a potential drug for treating myeloma bone disease by downregulating TRAF6 to inhibit the function and maturation of osteoclasts in multiple myeloma, and MG132 can be used in combination with radiotherapy to treat pancreatic cancer by inducing autophagy and downregulating TRAF6." (PMID 38931449, 2024). "TRAF6 promotes proliferation, migration and invasion of pancreatic cancer cells in vitro." (PMID 38825674, 2024). "However, in our cohort of 40 pancreatic cancer samples, only TRAF6 showed a correlation with prognosis." (PMID 38825674, 2024). "Additionally, studies have suggested a potential role of MG-132 in the treatment of pancreatic cancer, by reducing the expression of TRAF6 in tumor tissue and delaying tumor growth." (PMID 37165439, 2023). "In pancreatic cancer cells, miR-146a-5p exhibits significant upregulation and plays a role in regulating pancreatic cancer development and resistance to chemotherapy, primarily by suppressing the TRAF6/NF-κB p65/P-gp axis." (PMID 38139352, 2023). "In addition, studies have revealed that, in pancreatic cancer, TRAF6 is overexpressed and promotes tumorigenicity." (PMID 36010884, 2022). "Moreover, knockdown of TRAF6 in PC3 cells leads to reduced tumor growth in vivo, and knockdown of TRAF6 has also been shown to reduce growth of pancreatic cancer cells in vivo." (PMID 35853811, 2022).
pancreatic cancer (continued). "A combined treatment of ionizing radiation (IR) with a proteasome inhibitor (MG132) shows synergistic cell-killing effects and induces endoplasmic reticulum stress in human pancreatic cancer cells, which results from the increased autophagy induction through the inhibition of TRAF6." (PMID 33294443, 2020). "In addition, the downregulation of TRAF6 can destroy the tumorigenicity of pancreatic cancer cells in vitro and in vivo." (PMID 33294443, 2020). "For example, disorders of innate antibacterial response are of fundamental importance in the development of gastrointestinal cancers, including pancreatic cancer, and increased expression of TRAF6, TLR4, and NOD1 are detected in peripheral blood leukocytes of pancreatic cancer patients." (PMID 30294322, 2018). "STAT5A, TRAF6 are over-expressed in pancreatic cancer cells resistant to gemcitabine." (PMID 29023490, 2017). "Research has shown that pancreatic cancer cells recruit and reprogram macrophages through the CCL2/CCR2 signaling pathway, leading to the subsequent release of TWEAK via the CCL5/TRAF6/NF-κB pathway." (PMID 39972459, 2025). "By suggesting a pivotal role of PHLPP in the FKBP51/TRAF6/Akt complex, our results are only apparently in contrast with those reporting that FKBP51 overexpression in pancreatic cancer lowers pAkt levels." (PMID 36781840, 2023). "In addition, TRAF4, TRAF5, TRAF6, and TRAF7 demonstrate correlations with the degree of pancreatic cancer differentiation." (PMID 38825674, 2024).